PPARG (peroxisome proliferator activated receptor gamma)
Diseases named in the same sentence as PPARG in open-access papers (continued):
Sharing a sentence is not in itself a finding about the gene and the disease.
glioma (continued). "Third, the molecular mechanisms of PPARD and PPARG on glioma risk and prognosis are not elucidated in our study." (PMID 32198386, 2020). "PPARγ expression in gliomas further positively correlated with anti-angiogenic TSP-1 expression." (PMID 32785018, 2020). "Also, our earlier study showed additive effects of celecoxib (COX-2 inhibitor) and Fmoc-L-Leucine (PPARγ agonist) conjugated with biotinylated PAMAM G3 dendrimer in glioma and squamous cell carcinoma in vitro." (PMID 31652556, 2019). "In addition, PPARγ agonists inhibit in vitro motility and invasiveness of glioma cells and decrease glioma progression and improve survival in rodent models." (PMID 27347932, 2016). "In particular, the activation of PPARγ, which is expressed in high grade gliomas, has been shown to have several antineoplastic effects on human and rat glioma cell lines, inducing growth arrest and apoptosis in vitro and in vivo and inhibiting CD133+ cells expansion." (PMID 27313600, 2016). "To determine whether glutamate transporters in glioma cells could be modulated with PPARγ agonists as with astrocytes, we treated glioma cells with increasing concentrations of pioglitazone." (PMID 26046374, 2015). "In glioma samples, PPARγ expression was not linked to good prognosis but TZDs showed therapeutic efficacy." (PMID 25866814, 2015). "By highlighting the clinical relevance of elevated PPARγ levels in regulating expression of pro-apoptotic CIDEA in glioma, this study warrants further investigation directed towards evaluating efficacy of PPARγ inhibitors as effective anti-glioma therapeutic strategy." (PMID 27551468, 2015). "Pioglitazone and other PPARγ agonists may offer a novel treatment paradigm for the treatment of TAE through the promotion of extracellular glutamate clearance at both the glioma cell level and surrounding astrocytes." (PMID 26046374, 2015). "We conclude that PPARγ agonists may be therapeutically beneficial in the treatment of gliomas and furthermore suggest a novel role for these agents in the treatment of tumour associated seizures through the reduction in extracellular glutamate." (PMID 26046374, 2015). "Another effect of PPARγ agonists on glioma tissue is to reduce local tissue invasiveness." (PMID 24672773, 2014). "Interestingly, in four different glioma cell lines (A172, U87-MG, M059K,M059J) rosiglitazone led to inhibition of proliferation and induction ofapoptosis in a PPARγ-dependentway since there the antagonist GW9662 partially reverted this effect." (PMID 18725982, 2008). "Furthermore, troglitazonesensitized human glioma cells to TRAIL-induced apoptosis in a processindependent of PPARγ." (PMID 18725982, 2008). "Interestingly, PPARγ agonists induced a strong dose-dependent inhibition of proliferation in both glioma and gliosphere cells." (PMID 19018263, 2008). "Besides, PPARG is the most significant gene is responsible for all of these diseases and our shared hub genes AURKB and PLK1 are associated with the disease, respectively, stomach neoplasms and glioma." (PMID 38717954, 2024). "Moreover, PPARγ inactive derivatives ofknown PPARγ agonists which retain their propensity to counteract glioma progression might befurther developed to minimize potential PPARγmediated side effects in glioma patients." (PMID 18815619, 2008). "To examine the role of ALDOC or PPARγ signaling in GBM clinical cohorts, we assessed additional clinical data from the TCGA glioma dataset." (PMID 38741139, 2024). "The aim of this study was to evaluate the anti-glioma properties of celecoxib, Fmoc-L-Leucine, or their mixture against showing COX-2 and PPARγ expression, temozolomide-resistant U-118 MG glioma cell line." (PMID 38542198, 2024). "As most of the examined gliomas express or overexpress cyclooxygenase-2 (COX-2) and peroxisome proliferator-activated receptors γ (PPARγ), we decided to use these proteins as therapeutic targets." (PMID 38542198, 2024).
glioma (continued). "The mechanism of action of CXB and FL against glioma was COX-2 and PPARγ dependent and resulted in up-regulation of these factors." (PMID 38542198, 2024). "To examine the role of ALDOC or PPARγ signaling in GBM clinical cohorts, we examined additional clinical events recorded in the TCGA glioma dataset." (PMID 38741139, 2024). "It demonstrated that PPARD and PPARG polymorphisms might not contribute the prognosis of glioma." (PMID 32198386, 2020). "It was revealed that in many cancers including gliomas, the Wnt/β-catenin pathway and COX-2 expression are upregulated while PPARγ is downregulated." (PMID 31652556, 2019). "PPARγ agonists was able to up-regulate pro-apoptotic protein BAX and BAD expression, and then induced glioma cells apoptosis through releasing cytochrome C and activating the activation of caspase." (PMID 29642873, 2018). "Moreover, a retrospective study has demonstrated that diabetic GBM patients treated with thiazolidinedione drugs had an increased median survival, suggesting that PPARγ could represent a novel potential therapeutic target for the treatment of high grade glioma." (PMID 27313600, 2016). "The PPARγ agonist pioglitazone increases functional EAAT2 expression and reduces extracellular glutamate levels in both U87MG and U251MG glioma cells." (PMID 26046374, 2015). "Herein, we describe a novel mechanism of the PPARγ agonist, pioglitazone, in which we demonstrate its ability to increase EAAT2 expression and consequently extracellular glutamate levels in glioma cells." (PMID 26046374, 2015). "This study highlights for the first time the existence of (i) PPARγ-CIDEA regulatory loop in glioma and (ii) novel function of CIDEA as regulator of glioma cell survival." (PMID 27551468, 2015). "Since PUFAs are natural ligands of RXRα and PPARγ, effects of DHAO or GLAO supplementation on gene expression of these two receptors in rat glioma tumors were explored." (PMID 19014610, 2008). "PPARγ agonists have therefore been proposed as novel anti-neoplastic agents for the treatment of glioma, although currently these drugs have not been evaluated in serum-free glioma cell cultures or direct-to-xenograft animal models." (PMID 28491867, 2017). "In light of these recent reports demonstrating that PPARγ activation increases astrocytic GLT-1 expression in the context of ischemia and glioma cells, we showed that targeting PPARγ for GLT-1 modulation is also applicable in the context of HIV-1-associated brain inflammation." (PMID 28886715, 2017). "Although PPARα and PPARγ bind to the same cofactors, they appear to have differential effects on gene transcription in glioma cells; the role of PPARβ in glioma has not been characterized." (PMID 28491867, 2017). "In conclusion, this work demonstrated that the potential of the synthetic PPARγ agonist Pio as a novel promising therapy for glioma is not so obvious." (PMID 27313600, 2016). "Interestingly, increased CIDEA levels triggered glioma cell apoptosis, decreased HIF-1α activation and elevated PPARγ levels." (PMID 27551468, 2015). "At present, no clinical trials are underway with regards to treating glioma patients using PPARγ agonists." (PMID 24672773, 2014). "Today, there is increasing evidence that PPARγ agonists, including thiazolidinediones (TDZs) and nonthiazolidinediones, block the motility and invasiveness of glioma cells and other highly migratory tumor entities." (PMID 18815619, 2008). "In case the antiglioma properties oftroglitazone are solely or predominantly due to PPARγ activation, Δ2-troglitazoneshould display no or a considerably lower inhibitory potency on glioma cellviability than troglitazone." (PMID 18815619, 2008). "Therefore, molecular targets such as COX-2 and PPARγ do not seem to be appropriate therapeutic targets in glioma therapy." (PMID 38542198, 2024). "Nevertheless, the role of PPARG in glioma has not been elucidated." (PMID 32198386, 2020).
glioma (continued). "Moreover, we did not observe significantly association of PPARD and PPARG polymorphisms with OS and PFS of glioma patients (P > 0.05)." (PMID 32198386, 2020). "In in vitro rat cell models, activation of PPARγ transcription has been shown to upregulate catalase activity in normal astrocytes, but not in the glioma C6 cell line.Moreover, this effect was abolished in cells transfected with a dominant negative PPARγ construct." (PMID 24672773, 2014). "Increased levels of COX-2 and PPARγ expression in glioma cells did not result in increased CXB and FL toxicity in glioma cells when compared to lower expressing BJ and HaCaT cells." (PMID 38542198, 2024). "This was further supported by the finding that the PPARγ antagonist GW9662, either alone or in combination with troglitazone, does not affect glioma cell invasiveness in a Boyden chamber assay, suggesting that the effects observed are not mediated by PPARγ." (PMID 22194735, 2011). "We have shown that PPARγ inhibition by the investigational antagonist GW9662, either alone or in combinationwith troglitazone, does not affect rat F98 glioma cell invasiveness in a Boydenchamber assay, suggesting that the effects observed are not mediated by PPARγ." (PMID 18815619, 2008).
pulmonary hypertension (56 papers, 2007 to 2025). Increased pressure within the pulmonary circulation due to lung or heart disorder. "BRCC3 regulates the BMP signaling pathway and maintains pulmonary vascular homeostasis by deubiquitinating K472 and K475 sites of ALK2.BRCC3 deficiency exacerbates pulmonary arterial hypertension, and PPARγ agonists can partially alleviate its effects." (PMID 40385572, 2025). "Under hypoxia, increased HIF1α causes decreased expression of PPARγ, which increases proliferation of distal pulmonary arterial smooth muscle cells and promotes vascular remodeling, resulting in pulmonary hypertension." (PMID 33928137, 2021). "Later, PPARγ was implicated in cardiac development and in critical conditions such as pulmonary arterial hypertension (PAH) and kidney failure." (PMID 34638771, 2021). "Not only does pulmonary hypertension appear to be associated with reduced PPARγ expression, emerging evidence suggests that ligand-induced PPARγ activation attenuates pulmonary vasculardysfunction in animal models of pulmonary hypertension." (PMID 17710111, 2007). "However, studies have shown that loss of PPARγ (peroxisome proliferator-activated receptor γ) is associated with pulmonary hypertension." (PMID 34335086, 2021). "Furthermore, loss of PPARγ expression resulted in abnormal proliferationof apoptosis-resistant endothelial cells.The causal link between apoptosis and pulmonary hypertension-associatedalterations in PPARγ expression remains to be established." (PMID 17710111, 2007). "Moreover, loss of PPARγ expression is associated with the development of pulmonary hypertension induced by hypoxia; this finding is supported by a study showing that the expression of PPARγ is decreased in the lungs of rodents with pulmonary hypertension induced by chronic hypoxia exposure." (PMID 34434114, 2021). "In patients with pulmonary arterial hypertension, PPARγ expression has been found to be decreased in lung vascular lesions." (PMID 39435735, 2024). "FGF21 activation of the PPARγ pathway eliminates the production of inflammatory factors, suppresses pulmonary artery smooth muscle cell proliferation, and alleviates pulmonary arterial hypertension." (PMID 38733164, 2024). "Pioglitazone, the agonist of PPARγ, ameliorates mitochondrial disorders, reduces lipid deposition during, and thus prevents against severe pulmonary arterial hypertension and vascular remodeling." (PMID 38529329, 2024). "Unfortunately, there remains a paucity of evidence regarding the role of PPARγ in patients with pulmonary hypertension." (PMID 35204311, 2022). "Taken together, our results show that FGF21 can improve pulmonary vascular remodelling and collagen deposition by inhibiting the negative regulatory effects of miR‐130 on PPARγ and ultimately alleviating pulmonary hypertension." (PMID 34989130, 2022). "PPARγ directly binding to Smad3 plays a protective role, which has been reported in pulmonary arterial hypertension (PAH)." (PMID 36275905, 2022). "PPARγ, which is ubiquitously expressed, represents probably the best-studied TF in pulmonary hypertension." (PMID 36684555, 2022). "Reduced PPARγ expression was also demonstrated in vascular lesions in a rat model of severe pulmonary hypertension." (PMID 34335086, 2021). "In general, agonism of these receptors has been thought to promote cardiovascular health and an extensive literature in pulmonary hypertension suggests overall benefit due to PPARγ activation." (PMID 34488870, 2021). "Strong data have emerged regarding the positive role for pioglitazone, a PPARγ agonist in the treatment of pulmonary arterial hypertension and prevention of right ventricular failure in this condition." (PMID 34488870, 2021). "Most recent study found that PPARγ activation by PIO prevents pulmonary arterial hypertension, the pathogenesis of which is different from that HPH." (PMID 33192545, 2020).
pulmonary hypertension (continued). "A recent study showed that the EP4 agonist L-902, 688 is able to effectively increase PPARγ expression and attenuate pulmonary arterial hypertension." (PMID 32636842, 2020). "Previous studies have shown that the selective EP4 agonist L-902,688 can treat idiopathic pulmonary hypertension by activating peroxisome proliferator-activated receptor γ, PPARγ." (PMID 32636842, 2020). "Activation of PPARγ suppresses smooth muscle cell proliferation and migration by favorably regulating several potential pulmonary hypertension mediators." (PMID 29527168, 2018). "Here, an IP and PPARγ dual agonist (cefminox) was selected for further investigation of its mechanism of action and therapeutic effects in a hypoxia-induced rat model of pulmonary hypertension (PH)." (PMID 29527168, 2018). "PPARγ was shown to exert a beneficial role in pulmonary hypertension (PH) by attenuating, likely through activation of miR-98, ET1 expression." (PMID 28167956, 2017). "Last, peroxisome proliferator-activated receptor gamma (PPARγ), a transcription factor which is antiproliferative and proapoptotic, is decreased in pulmonary hypertension and contributes to endothelial proliferation." (PMID 27376089, 2016). "This appears to be PPARγ-dependent as mice with targeted deletion of the PPARγ gene in smooth muscle cell tissue spontaneously developed pulmonary arterial hypertension." (PMID 22778711, 2012). "PPARγ expression was decreased in patients with severe pulmonary hypertension, particularly around plexiform lesions." (PMID 22778711, 2012). "This FFL among CCL20, miR-1256 and PPARG may be a novel regulatory module in COVID-19 complicated with pulmonary hypertension." (PMID 38653779, 2024). "Using only 2 reference genes, we were able to isolate 12 shared TFs and 25 shared TF-miRNAs.by FFL tool, This FFL among CCL20, miR-1256 and PPARG may be a novel regulatory module in COVID-19 complicated with pulmonary hypertension." (PMID 38653779, 2024). "In addition, PPARγ also plays an important role in pulmonary hypertension, atherosclerotic and right heart failure cardiovascular disease." (PMID 38529329, 2024). "In a pulmonary hypertension rat model, the administration of pioglitazone, a PPARγ agonist, decreased RVSP and prevented RV dilation, which could in part be due to its impact on mitochondrial biogenesis." (PMID 35204311, 2022). "The miR-130/301 family expression levels are increased in pulmonary hypertension, resulting in a decrease in miR-204, miR-322 and miR-503 via peroxisome proliferator-activated receptor gamma (PPARG) and signal transducer and activator of transcription 3 (STAT3)." (PMID 33973623, 2021). "In addition, recent studies show that PPARγ activity regulates expression of miR-98, and in turn, miR-98 negatively regulates ET-1 expression in hypoxia-induced pulmonary hypertension." (PMID 33082140, 2020). "In addition to the results of VarElect analysis, we found that PPARγ had a high correlation with “pulmonary hypertension” phenotype in potential targets of genistein against PH." (PMID 31703458, 2019). "Recently, consistent data showed that hypoglycemic agents targeting PPARγ as well as renin–angiotensin system inhibitors and mineralocorticoid receptor blockers may influence pulmonary hemodynamics in different models of pulmonary hypertension." (PMID 30791536, 2019). "Treatment with the PPARγ agonist rosiglitazone prevents and reverses established hypoxia-induced pulmonary hypertension (HPH) by suppressing superoxide production and platelet-derived growth factor receptor-β signaling, and by increasing expression of the phosphatase and tensin homolog (PTEN)." (PMID 29527168, 2018). "Given the important antiproliferative, and antithrombotic and vasodilatory effects of PPARγ on the lung vasculature, upregulation of miR-27a may thus represent an important contributor to the development of pulmonary hypertension." (PMID 28167956, 2017).
pulmonary hypertension (continued). "Additionally, addition of the PPARγ agonist rosiglitazone prevents hyperoxia-induced alveolar simplification, pulmonary inflammation, airway hyperreactivity, and pulmonary hypertension." (PMID 28886148, 2017). "This pharmacological analysis, whilst limited as it is based on in vitro protocols, suggests that PPARβ/δ agonists may be superior to PPARγ agonists in the treatment of pulmonary hypertension." (PMID 20209098, 2010). "Thus, the role of PPARγ in the regulation of the Rho/Rho-kinasepathway during pulmonary hypertension remains a promising area for continuedinvestigation." (PMID 17710111, 2007). "In unpublished data, we have observed that exposure to chronic hypoxia (10%oxygen) for 3 weeks reduced lung PPARγ expression andcaused pulmonary hypertension in C57Bl/6 mice as indicated by elevation ofright ventricular systolic pressure and right ventricular hypertrophy." (PMID 17710111, 2007). "In a monocrotaline-induced pulmonary hypertension model, treatment with telmisartan protected endothelial cell function by inducing the expression of PPARγ, promoting the phosphorylation of Akt and eNOS, increasing the production of NO, and improving PPARγ-dependent vascular dilation." (PMID 37833942, 2023). "Pioglitazone, a kind of PPARγ agonist, relieved the RVH, pulmonary hypertension, and cardiomyocyte hypertrophy induced by chronic hypoxia." (PMID 35990266, 2022). "It has also been investigated that by pharmacological inhibition of PPARγ, RHAMM was upregulated in pulmonary arterial endothelial cells in a sheep model of pulmonary hypertension." (PMID 34335086, 2021). "Therefore, the following review will focus on selected mediators implicatedin pulmonary vascular dysfunction and evidence that PPARs, in particular PPARγ, participate in their regulation and may providea potential novel therapeutic target for the treatment of pulmonary hypertension." (PMID 17710111, 2007). "Pulmonary hypertension in female MRL/lpr (Lupus) mice was treated by administering the selective Cat S inhibitor Millipore-219393, which stimulated peroxisome proliferator-activated receptor-gamma (PPARγ) in the lungs to inhibit Cat S expression and pulmonary arterial remodeling." (PMID 36293172, 2022). "In a rat model of hypoxia-induced pulmonary hypertension, cefminox displayed therapeutic efficacy not inferior to that of the prostacyclin analog iloprost or the PPARγ agonist rosiglitazone." (PMID 29527168, 2018). "PPARγ, which could be regulated by TRIB3, was reported that inhibited TGF-β signaling and acted as a link between pro-proliferative TGF-β and anti-proliferative bone morphogenetic protein 2 (BMP2) signalings in vascular smooth muscle cells and inhibited pulmonary arterial hypertension." (PMID 33192545, 2020).